LCN2 (lipocalin 2)
Diseases named in the same sentence as LCN2 in open-access papers (continued):
Sharing a sentence is not in itself a finding about the gene and the disease.
depression (41 papers, 2016 to 2026). "LCN2, also known as neutrophil gelatinase-associated lipocalin, is an acute-phase protein involved in inflammation that plays a central role as a major mediator of inflammation and is an indicator of depression." (PMID 39273621, 2024). "The effect of LCN2 on the CNS is highly context-dependent; it has been implicated in anxiety, depression, and memory dysfunction, and exacerbates or attenuates CNS disease depending on the disease model." (PMID 39399497, 2024). "The level of LCN2, a pro-inflammatory cytokine mediator known to be associated with depression, was increased in vehicle-treated mice as assessed using real-time PCR (p < 0.001)." (PMID 39273621, 2024). "LCN2 has been shown to be associated with multiple biological behavioral activities such as pain hypersensitivity, cognitive function, emotion, depression and anxiety." (PMID 37543589, 2023). "Otherwise, serum LCN2 expression increased in patients with depression and was associated with depression score." (PMID 37543589, 2023). "Higher lipocalin 2 expression in patients brain has been found that significantly associated with depression scores." (PMID 34565419, 2021). "LCN2 is considered to be a potential diagnostic biomarker for depression." (PMID 37543589, 2023). "Our study provides potential association for LCN2 and comorbidity between depression and IS." (PMID 37065487, 2023). "In summary, our data revealed that Lcn2 is closely associated with anxiety symptoms, but the anxiety and depression symptoms caused by chronic skin inflammation may be irreversible." (PMID 36983014, 2023). "So, here decreased expression of lipocalin-2 in the body may be associated with increased inflammatory activities leading to depression." (PMID 37957650, 2023). "Interestingly, lipocalin 2 upregulation has also been reported that associated with sex-specific cognitive functioning in late-life depression." (PMID 34565419, 2021). "Our findings support the previous reports that the expression of lipocalin 2 in the brain may be an important regulator of cognitive symptoms, and increased lipocalin 2 levels is associated with depression or PTSD." (PMID 34565419, 2021). "Moreover, LCN2 has been reported to be highly expressed following ischemic stroke and to be closely associated with major depressive disorder." (PMID 34966272, 2021). "Several studies suggest that LCN2 deficiency and excess may be associated with depression." (PMID 41007258, 2025). "The sustained up-regulation of the IL-17 pathway and Lcn2 in chronic stress mirrors clinical observations in patients with anxiety or depression." (PMID 40649841, 2025). "A significant elevation in LCN2 levels in the hippocampus has been observed in patients diagnosed with attention deficit disorder who also meet the criteria for depression." (PMID 41007258, 2025). "Lipocalin-2 (LCN2), a pro-inflammatory cytokine mediator, has been associated with depression and is often accompanied by elevated levels of IL-6 and TNF-α." (PMID 39273621, 2024). "LCN2 has been found to be upregulated in both human patients with depression and animal models of depression induced by stress." (PMID 39273621, 2024). "In LCN2-deficient MRL/lpr mice, we observed an improvement in depression-like behaviors and learned helplessness." (PMID 39399497, 2024). "LCN2 is regulated by astrocytes, which can be a profound factor in depression owing to decreased astrocytes in the brain." (PMID 39273621, 2024). "A few other studies also observed the potency of LCN2 as an inflammatory marker for depression in elderly people." (PMID 38589429, 2024). "LCN2 expression is increased in the ovariectomized rat forced swim stress- and repeated social defeat stress-induced mouse models of depression." (PMID 39273621, 2024). "The protein known as NGAL, also referred to as lipocalin-2 or siderocalin, is recognized as a potential factor in the progression of AD and depression." (PMID 38877498, 2024).
depression (continued). "In conclusion, exposure to CS can significantly activate astrocytes and promote astrocyte‐derived Lcn2, which leads to neuronal death and drives depression‐like behavior in mice." (PMID 37864452, 2024). "In fact, increased LCN2 plasma levels were observed in depressed older patients, proposing LCN2 as a marker in the pathophysiology of late-life depression." (PMID 37168715, 2023). "Some earlier studies found the opposite result to our findings and suggested a correlation between elevated lipocalin-2 levels and late-life depression." (PMID 37957650, 2023). "In the present study, we found circulating lipocalin-2 levels were also increased in younger patients with depression, indicating lipocalin-2 plays an important function in the pathophysiology of depression." (PMID 37599893, 2023). "Compared with patients with the first episode, the plasma LCN2 level in patients with recurrent depression was higher." (PMID 37543589, 2023). "Further interventional studies are recommended for a better understanding of the role of IL-3 and lipocalin-2 in the pathophysiology of depression." (PMID 37957650, 2023). "Additionally, analysis of serum IL-3 and lipocalin-2 levels provided significant diagnostic value for MDD patients and can be an effective indicator of probable depression development." (PMID 37957650, 2023). "Vichaya found that LCN2 is dispensable for sterile inflammation-induced sickness and depression-like behavior." (PMID 32605546, 2020). "Multiple studies have identified links between LCN2, depression and behavior." (PMID 38597406, 2024). "Recently, LCN2 was suggested as a marker of late-life depression." (PMID 39273621, 2024). "The results suggest that patients with depression have higher serum LCN2 levels." (PMID 37543589, 2023). "Another study by the team showed that depression in patients with chronic heart failure was associated with elevated plasma LCN2, but not with the clinical severity of the underlying disease." (PMID 37543589, 2023). "The roles of LCN2 in IS and depression have been proved recently." (PMID 37065487, 2023). "The prevalence of depression is elevated in older people and, taking into consideration our results, aged LCN2-null mice could constitute an effective animal model to explore putative novel therapeutic approaches in late-life depression." (PMID 37168715, 2023). "Therefore, altered serum levels of IL-3 have been observed in patients with mood disorders and lipocalin-2 in patients with late-life depression." (PMID 37957650, 2023). "The finding of altered peripheral levels of IL-3 and lipocalin-2 in MDD patients may indicate a strong relationship between the pathophysiology of depression and these biomarkers." (PMID 37957650, 2023). "Furthermore, Lcn2 modulates several behavioral responses such as cognitive function, depression, neuronal excitability and anxiety." (PMID 31936294, 2020). "Still, and even though the immobility time in LCN2-null mice decreased with age, learned helplessness persisted in aged mice when compared to aged-matched Wt mice, which may suggest a putative involvement of LCN2 in late depression." (PMID 37168715, 2023). "Lipocalin 2 (LCN2), as an acute phase protein, is involved in the development of acute ischemic stroke (AIS), and its expression is up-regulated in patients with depression, suggesting that there is a potential correlation between serum LCN2 and depression." (PMID 37543589, 2023). "The present study aimed to evaluate serum IL-3 and lipocalin-2 in MDD patients and healthy controls (HCs) to understand their role in the pathophysiology and development of depression." (PMID 37957650, 2023). "The study further revealed that the concentration of LCN2 was higher in patients with a recurrent depression compared to those with a first episode and independent of antidepressant treatment." (PMID 27729871, 2016).
depression (continued). "After adjusting for multiple confounding factors, high baseline serum LCN2 is an independent risk factor for PSD at discharge, and it showed significant diagnostic accuracy in distinguishing PSD patients from patients without depression." (PMID 37543589, 2023). "The relationship between LCN2 and depression should not be ignored." (PMID 37543589, 2023). "In addition, lipocalin 2 (Lcn2) was upregulated in PVT of mice with depressive behavior induced by dextran sulfate sodium (DSS), and the depressive behavior was reduced when Lcn2 was silenced, which indicated that the increase of Lcn2 in PVT was an important pathway of depression induced by DSS." (PMID 41585794, 2025).
Cirrhosis (39 papers, 2012 to 2025). A chronic disorder of the liver in which liver tissue becomes scarred and is partially replaced by regenerative nodules and fibrotic tissue resulting in loss of liver function. "We found that, for LCN2, serum levels were elevated in cirrhosis patients compared with healthy controls; however, the significance was much lower than that from a comparison between the cirrhosis and HCC groups." (PMID 35308139, 2022). "In the Child–Pugh class of decompensated cirrhosis, urinary lipocalin-2/IL-18 levels increased and GFR decreased significantly." (PMID 34831270, 2021). "Urine levels of IL-18 and lipocalin-2 from patients with cirrhosis discriminate between those with ATN and other types of kidney impairments." (PMID 34831270, 2021). "Renal expression of lipocalin-2 is significantly increased in decompensated cirrhosis with increased circulating TNFα and acute renal injury." (PMID 33513830, 2021). "In line with this assumption, numerous studies correlated LCN2 with general hepatic injury, inflammation, infection, cirrhosis, and fatty liver disorders." (PMID 27729871, 2016). "In line, Ariza and colleagues found in a cohort of more than 700 patients with cirrhosis that urine LCN2 was markedly increased in the patients when compared to healthy control samples, establishing urine LCN2 as a prognostic marker of cirrhosis." (PMID 27729871, 2016). "Finally, as ductular reaction aggravated with the progression of fibrosis to cirrhosis, immunofluorescent staining showed increasing numbers of LCN2+ LPCs surrounded by more macrophages in liver tissues." (PMID 37784089, 2023). "A clinical study of 716 patients with cirrhosis showed that LCN2 might be a biomarker of acute-on-chronic liver failure and prognosis in cirrhosis." (PMID 34954190, 2022). "Lcn2 is also known as neutrophil gelatinase-associated lipocalin (NGAL) which transports lipophilic molecules such as steroids, lipopolysaccharide, and iron in circulation and is considered as a prognostic biomarker of cirrhosis." (PMID 32622362, 2020). "In 2010 urinary LCN2 levels were correlated to hepatic fibrosis and cirrhosis in HCV patients." (PMID 27729871, 2016). "The measurement of LCN2 in urinary samples could be useful to predict the outcome of cirrhosis, liver transplantation rejection, and hepatic fibrosis." (PMID 27729871, 2016). "Further they noticed that there was positive correlation between lipocalin 2 (LCN2) and MMP-9 and negative correlation with tissue inhibitors of MMP (TIMPs) in the 3 studied groups suggesting that this may have role in progression of cirrhosis and hepatocellular carcinoma." (PMID 32856853, 2020).
inflammatory bowel disease (39 papers, 2012 to 2026). A spectrum of small and large bowel inflammatory diseases of unknown etiology. "These include the gene S100A9, which forms the heterodimer calprotectin, and the antimicrobial peptide lipocalin (LCN2, also known as NGAL (Neutrophil Gelatinase-Associated Lipocalin)), both of which are used as fecal biomarkers for disease activity in inflammatory bowel disease." (PMID 33198309, 2020). "Furthermore, an impaired expression of DEF-5 and LCN2 and the over-production of the pro-inflammatory cytokine IL1β have been closely associated with inflammatory bowel disease." (PMID 23754197, 2013). "With the development of standardized protocols in future studies, one can envisage that the additional analysis of fecal lipocalin-2 levels could provide a diagnostic and prognostic advantage in comparison to the sole analysis of fecal calprotectin concentrations in inflammatory bowel diseases." (PMID 37189804, 2023). "Abnormal expression of Lcn2 in certain disease states, such as inflammatory bowel disease, can disrupt gut metabolism." (PMID 39051782, 2024). "On the other hand, lipocalin-2 levels were comparable in the stool of patients with infectious enterocolitis and inflammatory bowel diseases." (PMID 37189804, 2023). "Similar trends were provided by others, documenting higher fecal lipocalin-2 levels in active compared to quiescent inflammatory bowel diseases." (PMID 37189804, 2023). "Lipocalin-2 is increased in the serum of humans with inflammatory bowel disease and is correlated with the activity of this disease." (PMID 37092455, 2023). "In summary, several studies revealed promise to develop fecal lipocalin-2 levels as a biomarker for inflammatory bowel diseases." (PMID 37189804, 2023). "This includes increased urinary adiponectin, lipocalin-2, leptin and interleukin-6 (IL-6) levels in renal diseases and an association of elevated urinary chemerin as well as urinary and fecal lipocalin-2 levels with active inflammatory bowel diseases." (PMID 37189804, 2023). "During inflammatory bowel disease, high mucosal and fecal concentrations of lipocalin-2 occur, but lipocalin-2 can also be used as a more general biomarker of intestinal inflammation." (PMID 36430985, 2022). "Oxidative stress also induces a strong expression of LCN2 protein in colonic epithelial cells in inflammatory bowel disease." (PMID 35440572, 2022). "Previous studies in patients with inflammatory bowel disease observed a positive correlation between lipocalin-2 and calprotectin stool concentrations." (PMID 36430985, 2022). "We next examined the mRNA levels of numerous proinflammatory cytokines, chemokines, and lipocalin-2 (Lcn2), a potential biomarker for inflammatory bowel disease." (PMID 35055106, 2022). "Other groups have shown in models of inflammatory bowel disease that LCN2 is a host defense protein protecting against intestinal inflammation by controlling the bacterial community." (PMID 34884961, 2021). "In contrast to calprotectin, the expression of lipocalin-2 in biopsies from the ileum and rectum of histologically healed patients with inflammatory bowel diseases remained elevated compared with controls, showing its sensitivity in states of lower-grade inflammation." (PMID 37866678, 2024). "Measurement of additional biomarkers may improve the diagnosis of inflammatory bowel diseases, and determining fecal lipocalin-2 levels may represent an attractive option." (PMID 37189804, 2023). "Likewise, in another cohort of inflammatory bowel diseases, fecal lipocalin-2 levels positively correlated with disease severity and endoscopic activity scores." (PMID 37189804, 2023). "Besides, LCN2 has been demonstrated as a biomarker for inflammatory bowel disease, vascular dementia, neuropsychiatric lupus, and subarachnoid hemorrhage outcome." (PMID 35495713, 2022). "Fecal LCN2 could be used as a biomarker for detecting endoscopic activity in patients with inflammatory bowel diseases." (PMID 35111677, 2021).
inflammatory bowel disease (continued). "Although Lcn2/NGAL expression is increased in the inflamed intestinal tissues of patients with inflammatory bowel disease, the role of Lcn2/NGAL in the development of intestinal inflammation remains unclear." (PMID 27734904, 2016). "LCN2 also plays a role in the pathophysiology of inflammatory bowel disease (IBD) and upregulates the NLRP3 inflammasome via NF‐κB activation." (PMID 37353794, 2023). "Of interest, bacteria thought to be beneficial for inflammatory bowel disease (IBD) such as Anaerobutyricum, Blautia, and Roseburia, were reduced in fecal Lcn-2-high MS patients." (PMID 36341389, 2022). "For example, in the LCN2/CFH interaction, expression of the former is observed in kidney and liver injury, lung inflammation and Inflammatory bowel disease-positive intestinal epithelium." (PMID 37778719, 2023). "DGE of the lower villus zone revealed that NEC epithelial cells exhibited substantial increase in the antimicrobial genes LCN2, REG1A, REG1B, and DMBT1, genes previously shown to be elevated in inflamed epithelium associated with inflammatory bowel disease (IBD)." (PMID 37205711, 2023). "Moreover, lipocalin 2 modulated by PPARG could be a potential pathway involved in concurrent inflammation and ankylosis in inflammatory bowel diseases and ankylosing spondylitis." (PMID 37254181, 2023).